LGR5 (leucine rich repeat containing G protein-coupled receptor 5)
Diseases named in the same sentence as LGR5 in open-access papers (continued):
Sharing a sentence is not in itself a finding about the gene and the disease.
tumor (continued). "In another study, it was found that tumor cells expressing intestinal stem cell marker LGR5 are the CSCs to fuel growth of intestinal adenomas." (PMID 36765715, 2023). "The role of LGR5 in the stimulation of tumour invasion and metastasis has also been demonstrated in other cancer cells." (PMID 38201468, 2023). "Deconvolution analyses also revealed increases in epithelial cells with gene expression signatures of IFE and Lgr5+ve derived cell populations during disease progression indicating potential tumour initiation in these cell compartments." (PMID 37626054, 2023). "LGR5+ cells eventually appear via cell plasticity in nascent metastases and are indispensable in maintaining tumor growth." (PMID 37894295, 2023). "After depletion of Lgr5+ cells from primary Apcmin/+;KrasG12D-induced tumours, Lgr5− cells displayed activated c-Myc pathway and overrepresentation of genes implicated in cell-cycle progression." (PMID 37259089, 2023). "For the direct visualization of LGR5 expressing tumor stem cell, murine tumor organoids were cultured from previous DEN‐induced primary liver tumors from LGR5‐GFP‐CreERT/Rosa26‐iDTR transgenic mice." (PMID 37578396, 2023). "Immunofluorescence (IF) staining were further adopted to confirm the tumor formation and evaluate the geographical distribution of LGR5‐GFP+ cells in the liver tumors." (PMID 37578396, 2023). "Subsequently, it was postulated that metastases are started by disseminated differentiated tumor cells that, once reaching the liver, through plasticity, produce LGR5+ cancer stem cells." (PMID 37627048, 2023). "We also found that co‐engraftment of liver tumor organoids with CAFs resulted in dramatic higher number of LGR5+ cells in the formed tumors when compared with engrafting tumor organoids alone." (PMID 37578396, 2023). "The co‐culture organoid model composed of murine liver tumor LGR5+ tumor‐initiating cells and CAFs in 3D co‐culture was successfully established, with the intention to investigate their mutual interaction." (PMID 37578396, 2023). "The role of CSCs with a leucine-rich repeat-containing G-protein-coupled receptor 5 (Lgr5)(+) phenotype, essential for tumor growth and metastasis formation (e.g., in the liver), has also been demonstrated in growing CRC tumor tissues." (PMID 37760539, 2023). "Published data also revealed that LGR5 expressing intestinal tumor stem cell will be dramatically influenced by the intestinal CAF." (PMID 37578396, 2023). "After tumor initiation, we found that the supplement of CAFs with LGR5+ tumor cells formed significantly larger tumors compared with engrafting LGR5+ cells alone (0.6 ± 0.2 vs. 0.3 ± 0.2 g, n = 5, p < 0.05)." (PMID 37578396, 2023). "qPCR analysis showed that the expression of CD133, CD44, and OCT4 and SOX2, EpCAM, and LGR5 in CSC sphere cells enriched after the addition of micro serum was higher than that in tumor cell spheres enriched in serum-free medium." (PMID 37639070, 2023). "Subsequently, immunodeficient mouse‐based xenograft model was further adopted to evaluate the influence of CAFs to LGR5 tumor stem cell, tumor formation, and metastasis." (PMID 37578396, 2023). "In contrast, LGR5 had a significantly lower IRS in normal adjacent tissue than in tumor tissue, with a calculated IRS difference of 1.33 ± 0.36 (p < 0.0004)." (PMID 37998393, 2023). "They observe that as compared to damaged liver, LGR5 expression levels vary greatly but are much higher in tumor cells." (PMID 37547759, 2023). "Most importantly, co‐engraftment dramatically increased the probability of abdominal metastasis (7/8) compared with mono‐engraftment of LGR5+ tumor cells (1/8)." (PMID 37578396, 2023). "The results of experiments with tumour xenografts in nude mice revealed that LGR5 showed strong tumorigenic properties." (PMID 38201468, 2023). "A recent study revealed that LGR5 + colon CSCs were responsible for driving tumor re-growth after ablation." (PMID 37328854, 2023).
tumor (continued). "In the CAC mouse model, MUC1-C can form a transcription complex with MYC and act on the LGR5 promoter region, thereby activating LGR5 expression and tumor growth." (PMID 37875976, 2023). "This study shows that LGR5+ compartments are present in liver cancer and exhibit characteristics of TICs/CSCs, such exhibit an improved ability to generate tumor organoids in culture and allografts in mice as well as resistance to standard anticancer therapy." (PMID 37547759, 2023). "Systematic reviews and meta-analyses have shown that LGR5 is a predictive factor for tumor invasion, metastasis, and resistance to chemotherapy and an indicator of poor prognosis in GC." (PMID 37460910, 2023). "Meanwhile, the interaction between tumor LGR5 stem cells and tumor fibroblasts is also under investigation, but the mechanism of action is still unclear and needs further investigation." (PMID 37578396, 2023). "Subsequently, the 3D co‐culture organoid system was followed to construct with the intention to investigate the interaction between CAFs and LGR5+ expressing tumor cells." (PMID 37578396, 2023). "In 2017, Toshiro Sato confirmed that LGR5 + tumour cells have the characteristics of tumour stem cells, revealing their self-renewal and differentiation capabilities." (PMID 37537666, 2023). "Several studies have shown that a fraction of LGR5+ stem-like tumor cells are responsible for the progression of CRC." (PMID 37627048, 2023). "Consistently, we further to investigate the influence of CAFs to LGR5‐expressing cell regarding the tumor initiation and growth." (PMID 37578396, 2023). "Tsc1 co-deletion with Apc in ISCs resulted in a greater tumour burden, supporting the notion that refeeding via mTORC1 stimulation promotes the tumourigenicity of Lgr5+ ISCs." (PMID 36711807, 2023). "The resulting subset of tumors follow distinct evolutionary paths when compared to Wnt/Myc-driven Lgr5-derived tumorigenesis, and are characterized by an inflammatory tumor phenotype more prone to infiltration from the tumor micro-environment." (PMID 36711533, 2023). "Along with tumor cells dedifferentiation, the expression of WNT target genes (e.g., Lgr5 and Cd44) associated with 'stem-like' colon cancer cells were remarkably elevated in tumor organoids." (PMID 35541903, 2022). "In contrast, in SCs lined by NTE, LGR5 expression was less often observed in the tumor epithelial cells with much lower H-scores (7 of 12 spots, [mean ± SD]: 3.9 ± 6.8)." (PMID 35778589, 2022). "With the exception of Olfm4, the expression of markers for active (Lgr5) and quiescent (Hopx) stem cell populations were maintained in tumor organoids, even at the highest CAP dose (80 W)." (PMID 35169122, 2022). "IL25 treated CRC cells substantially enhanced the expression levels of CD133 and LGR5, the formation of tumor organoid and sphere, thus decreasing the sensitivity to oxaliplatin of CRC cells." (PMID 35359953, 2022). "This interestingly showed the mechanical induction of the intestinal niche cells of Lgr5+ SC by magnetically-mimicked tumor growth pressure, in the colon." (PMID 35177769, 2022). "We thus used the Ret inhibitor Vande to evaluate the role of Ret in the mechanically induced increase in Lgr5+ cell number by magnetically-mimicked tumor growth pressure, in the Apc heterozygous genetic background." (PMID 35177769, 2022). "To determine the effect of LGR5 on tumor growth, we induced LGR5 expression in OVCAR-3 and SNU-8 cells." (PMID 35778589, 2022). "We found a significant increase in the number of Lgr5+ cells after 1 month of magnetically induced tumor growth pressure stress exerted on Apc 3 month-old mice colon." (PMID 35177769, 2022). "Lgr5+ stem cells have been demonstrated to be the cells of origin of multiple tumor types in the stomach, intestine, and liver." (PMID 35778589, 2022). "CSCs, as the tumor’s clonogenic core, have specific markers such as leucine-rich repeat-containing G-protein-coupled receptor 5 (LGR5)." (PMID 36348319, 2022).
tumor (continued). "Expression of LGR5 was significantly higher in tumor tissues while VSIG4 had higher expression levels in normal tissues (p < 0.05)." (PMID 36186438, 2022). "Emp1-TOMhigh cells were largely enriched at tumor buds which, in contrast, contained few Lgr5-EGFP+ cells." (PMID 36352230, 2022). "Additional CSC markers Sox2, CD44v6, and Aldh1/2 expression were analysed after magnetically induced permanent tumor growth pressure in vivo in Apc;Lgr5-EGFP mice." (PMID 35177769, 2022). "Taken together, these findings indicate a tumor-suppressive role for LGR5 in the progression of HGSC." (PMID 35778589, 2022). "We confirmed through scratch and Transwell experiment that high LGR5 expression can promote the migration and invasion of tumor cells." (PMID 36288272, 2022). "Here we find that the mechanical activation of Ret by tumor growth pressure is upstream of the β-cat target gene Lgr5 in SC and CSC in vivo, thanks to the use of the Vande specific inhibitor of Ret mechanical induction of phosphorylation in mice colon." (PMID 35177769, 2022). "Tumor-resident Lgr5+ cells exist in GC, but their cellular and genetical features as CSCs have not been established." (PMID 35743714, 2022). "High LGR5 expression has been previously reported to be closely related to tumor proliferation and invasion and has been detected in various malignancies." (PMID 36288272, 2022). "Limiting dilution transplants of fluorescence-activated cell sorting (FACS)-isolated tumor cells revealed that tumor-initiating capacity was increased in the Lgr5+ cell fractions." (PMID 36358834, 2022). "In parallel, they produced the orthotopic cancer organoid transplantation models to evaluate tumor-resident Lgr5+ stem cells via in vivo ablation." (PMID 35743714, 2022). "By constructing a recombinant LGR5 plasmid to transfect tumor cells to overexpress LGR5 protein, the regulatory pathways and molecular mechanisms of EMT and phenotypic transformation of stem cells induced by inflammatory factors were verified." (PMID 36288272, 2022). "Wnt-target gene (Axin2, Myc and Lgr5) expression was increased in the small intestine tumour tissue compared to normal tissue from both ApcMin/+/Setd7−/− and ApcMin/+/Setd7+/− mice, but more in tumours from ApcMin/+/Setd7+/−." (PMID 35326563, 2022). "The use of VP to increase the phosphorylation level of YAP had little effect on LGR5 expression, but the invasion ability of tumor cells was significantly decreased." (PMID 36288272, 2022). "In contrast, ID3 + cells highly expressed genes such as MDK, ZEB1, and LGR5 that play important roles in tumor stemness." (PMID 35347134, 2022). "A similar increase in Lgr5+ SC number was also observed after 1 month of tumor mechanical stress in the Apc heterozygous strain." (PMID 35177769, 2022). "(B, D) Quantification of the frequency of tumour regions expressing exclusively one probe or co-expressing two probes (yellow): Thbs1 only in red or Lgr5 only in green (B); Thbs1 only in red or Sca1 only in green (D)." (PMID 35543624, 2022). "Inoculation of this MTO line into the caecum further validated our previous observations that invasion fronts, tumor buds and micrometastases seldom contain Lgr5+ cells." (PMID 36352230, 2022). "Instead, tumours are supported by proliferative Lgr5 cells, which try to replenish the stem cell pool." (PMID 35563449, 2022). "The tumor-resident Lgr5+ stem cells are critical to the initiation and maintenance of tumor and are obligatory for establishing the metastasis in GC in vivo." (PMID 35743714, 2022). "Mechanistically, LGR5+ gastric cardia stem cells present in the murine BE-like lesion were suggestive of gastric progenitors arising under tumor-promoting inflammatory conditions." (PMID 36233047, 2022).
tumor (continued). "Several reports have outlined the stimulatory effects of Lgr5 in tumor growth, especially in gastrointestinal cancers, through the regulation of CSC stemness, EMT, and tumor cell proliferation." (PMID 34453639, 2021). "Subsequent implantation of these engineered tumor organoids into mice led to lineage tracing and ablation experiments to study the role of Lgr5+ cells or other cell types of interest during tumor progression and metastasis." (PMID 33671641, 2021). "Of note, excess dietary cholesterol also stimulates ISC proliferation and promotes tumour formation in ApcMin/+ mice, but does so directly by impacting phospholipid remodelling and the membrane lipid composition of Lgr5+ ISCs." (PMID 33673710, 2021). "As multiple Lgr5+ and Lgr5− populations exhibit phenotypic plasticity and tumour-initiating potential within the intestine, questions remain as to the likely cell(s)-of-origin of the emergent tumours in the BA model and the serrated neoplasia pathway." (PMID 34103493, 2021). "The same approach allows labelling of human tumor organoids from patient samples while simultaneously introducing transgenes that enable inducible and selective ablation of Lgr5+ cells." (PMID 33671641, 2021). "Encouragingly, antibody-mediated blockade of RSPO3 inhibited the growth of PTPRK-RSPO3-fusion-positive human tumour xenografts, compromising the expression of stemness genes (e.g., LGR5, ASCL2, LRIG1, TERT) and promoting differentiation." (PMID 33673710, 2021). "An anti-LGR5 antibody-drug conjugate inhibited tumor growth and tumor regression in two LGR5-positive xenograft models, LoVoX1.1 (colon cell line) and D5124 (primary human pancreatic)." (PMID 34946546, 2021). "Ablation of Lgr5+ cells in experimental liver metastasis after injection of tumor organoids into the portal vein also ablated the metastatic tumor burden to barely detectable levels." (PMID 33671641, 2021). "In mouse, Lgr5 expression marks stem cells in normal small intestine and tumor tissues, demonstrating that tumor tissues consist of heterogeneous cells mirroring the cellular hierarchy of the normal intestine." (PMID 33711267, 2021). "While the expression levels of miR-340 and FOXO1 genes in tumor samples displayed a significant reduction (p ≤ 0.001), the LGR5 gene presented a significant increase in expression (p ≤ 0.0001)." (PMID 33718760, 2021). "Given that a small number of cells are infected by STm in vivo, and Lgr5+ cells showed greater propensity to be infected and undergo cell death, we assessed Lgr5-GFP tumor organoids by flow cytometry." (PMID 34710062, 2021). "Since then, reports have identified CD44+ cells to be enriched for CSC-like properties, CD26+ cells capable of initiating tumor formation and facilitating EMT, and LGR5+ normal intestinal SCs serving as the tumor cells of origin." (PMID 33763422, 2021). "Transplanted CRISPR-engineered organoids in mice showed limited tumor progression or even regression after the ablation of LGR5+ cells." (PMID 34071313, 2021). "After the drug removal, these LGR5-negative cells reverted to the LGR5-positive state to reconstitute the entire tumor, suggesting a pool of CSCs with the ability to interconvert between two distinct states." (PMID 34582650, 2021). "APC truncation or post-irradiation depletion of Lgr5+ ISCs induces radioresistant Krt19+Lgr5− upper-crypt progenitors to dedifferentiate, via an Lgr5+ state, spawning tumours both in the small intestine and colon." (PMID 33673710, 2021). "We also detected two WNT mediators of GPX2 and OLFM4, which can be activated by Lgr5 to drive tumor progression." (PMID 34764257, 2021). "Consistent with this, residual drug-resistant LGR5− cells that can reconstitute tumour growth, following LGR5+ cell depletion, express the EGF-family member EREG." (PMID 33673710, 2021). "This persisting, slow-cycling LGR5-expressing population was characterized by active Wnt signaling, and combined Wnt and Hh inhibition resulted in tumor regression." (PMID 34071428, 2021).